RPL24 (ribosomal protein L24)
Description:
Component of the large ribosomal subunit. The ribosome is a large ribonucleoprotein complex responsible for the synthesis of proteins in the cell.
Synonyms: L24; eL24; HEL-S-310
Tractability: Small molecule: an approved drug acts on it; a structure with a bound ligand is known; a high-quality ligand is known. PROTAC: UniProt records ubiquitination sites on it; ubiquitination databases record sites on it; its protein half-life has been measured; a small molecule that binds it is known. Other modalities: a drug acting on it is in phase 2 or 3 trials.
Target class: Other cytosolic protein
Gene: Protein-coding gene on chromosome 3 (101,681,091 to 101,686,757, reverse strand). Ensembl gene ENSG00000114391.
Subcellular location: Cytoplasm
Subcellular location (Human Protein Atlas): Cytosol; Endoplasmic reticulum
Pathways (Reactome):
Metabolism of proteins: Eukaryotic Translation Termination; Formation of a pool of free 40S subunits; GTP hydrolysis and joining of the 60S ribosomal subunit; L13a-mediated translational silencing of Ceruloplasmin expression; PELO:HBS1L and ABCE1 dissociate a ribosome on a non-stop mRNA; Peptide chain elongation; Ribosome Quality Control (RQC) complex extracts and degrades nascent peptide; SRP-dependent cotranslational protein targeting to membrane; ZNF598 and the Ribosome-associated Quality Trigger (RQT) complex dissociate a ribosome stalled on a no-go mRNA
Metabolism of RNA: Major pathway of rRNA processing in the nucleolus and cytosol; Nonsense Mediated Decay (NMD) enhanced by the Exon Junction Complex (EJC); Nonsense Mediated Decay (NMD) independent of the Exon Junction Complex (EJC)
Cellular responses to stimuli: Response of EIF2AK4 (GCN2) to amino acid deficiency
Developmental Biology: Regulation of expression of SLITs and ROBOs
Disease: Viral mRNA Translation
Metabolism: Selenocysteine synthesis
Gene Ontology:
Molecular function: cadherin binding; protein binding; RNA binding; structural constituent of ribosome
Biological process: cytoplasmic translation; negative regulation of myoblast fusion; spermatogenesis; striated muscle contraction; translation
Cellular component: cytoplasm; cytosol; cytosolic large ribosomal subunit; cytosolic ribosome; endoplasmic reticulum; extracellular exosome; membrane; synapse
Genetic constraint (gnomAD): Loss-of-function variants: 5 observed, 17.97 expected, observed/expected ratio (o/e) 0.28, 90% interval 0.14 to 0.58. The upper end of that interval is the gene's LOEUF score, 0.58, which puts it in group 2 of 6, group 1 being the genes least tolerant of losing a copy. Missense variants: 75 observed, 150.9 expected, observed/expected ratio (o/e) 0.5, 90% interval 0.41 to 0.6. Synonymous variants: 52 observed, 48.69 expected, observed/expected ratio (o/e) 1.07, 90% interval 0.85 to 1.35.
Homologues: Orthologues: dog RPL24 (100% identical), guinea pig RPL24 (100% identical), pig RPL24 (99% identical), rat Rpl24l1 (92% identical), tropical clawed frog rpl24 (92% identical), zebrafish rpl24 (89% identical), Drosophila melanogaster RpL24 (64% identical), Caenorhabditis elegans rpl-24.1 (54% identical). Paralogues in human: RSL24D1 (31% identical).
Diseases named in the same sentence as RPL24 in open-access papers:
RPL24 is named in the same sentence as 29 diseases in open-access papers, as found by Europe PMC text mining. Sharing a sentence is not in itself a finding about the gene and the disease. The quoted sentences say what the papers report.
breast carcinoma (4 papers, 2014 to 2021). "In agreement with this, RNAi against RPL24 in human breast cancer cell lines dramatically reduced proliferation." (PMID 34895463, 2021). "Third, a previous study provided new evidence that RPL24 expression is common in human breast tumors, but that depletion or structural alteration of RPL24 can significantly impair human breast cancer cell viability." (PMID 32039517, 2020). "Depletion of RPL24 in breast cancer cells by >70% reduced cell viability by 80% and decreased protein expression of the eIF4E-dependently translated proteins cyclin D1 (75%), survivin (46%) and NBS1 (30%) without altering GAPDH or beta-tubulin levels." (PMID 24970821, 2014). "Since the translation-dependent checkpoint mechanism remains undefined, we evaluated the impact of RPL24 depletion in a model human breast cancer cell line, SKBR3, sensitive to eIF4E-regulated and cap-dependent translation inhibition." (PMID 24970821, 2014). "Using a public dataset of RNA profiles reported from 43 pairs of breast cancer and normal breast samples, we determined that approximately two-thirds of the breast cancers showed increased RPL24 transcript levels relative to their matched normal breast sample." (PMID 24970821, 2014). "By analyzing a public dataset of matched human breast cancers and normal mammary tissue, we found that breast cancers express significantly more RPL24 than matched normal breast samples." (PMID 24970821, 2014). "Given the known role of RPL24 in murine tumorigenesis and therapeutic interest in eIF4E-driven human breast cancers, we asked if RPL24 expression is also altered during human breast tumorigenesis, and observed that most human breast cancers overexpress RPL24 relative to normal breast tissue." (PMID 24970821, 2014).
COVID-19 (3 papers, 2022 to 2023). A disease caused by infection with severe acute respiratory syndrome coronavirus 2. "Collectively, our association analyses highlighted six common variants identified in previous GWAS or by the HGI—in/near LZTFL1, MHC, DPP9, IFNAR2, RPL24 and FOXP4—that are associated with COVID-19 as well as disease severity among cases." (PMID 35241825, 2022). "However, other loci as those in 3q12.3 (near RPL24) and 19p13.3 (near DPP9), previously found associated with COVID-19 severity, were not replicated in the SCOURGE Europeans." (PMID 35708486, 2022).
lymphoma (3 papers, 2011 to 2022). A malignant (clonal) proliferation of B- lymphocytes or T- lymphocytes which involves the lymph nodes, bone marrow and/or extranodal sites. "Haplo-insufficiency of the ribosomal proteins eL24 (RPL24) or eL38 (RPL38) has been shown to prevent lymphoma induction in a transgenic EμMyc mouse model." (PMID 36140189, 2022). "Moreover, the mandatory role of the ribosome in Myc-dependent transformation was elegantly demonstrated as haploinsufficiency of the eL24 (RPL24) or eL38 (RPL38) ribosomal proteins prevented lymphoma induction in a transgenic in EμMyc mouse model." (PMID 32151059, 2020).
breast tumors (2 papers, 2014 to 2020). "This is the first study implicating a role for RPL24 expression in human breast tumors and in regulating protein translation necessary for breast tumorigenesis." (PMID 24970821, 2014).
cervical cancer (2 papers, 2023 to 2024). A primary or metastatic malignant neoplasm involving the cervix. "Correlation between therapeutic effect and RPL24 expression after CCRT in 40 patients with cervical cancer." (PMID 37920171, 2023). "Additionally, RPL24 may play a role in liver regeneration and could serve as a potential prognostic biomarker for cervical cancer when treated with cisplatin and concurrent chemoradiotherapy." (PMID 38787142, 2024).
colorectal cancer (2 papers, 2021 to 2023). A primary or metastatic malignant neoplasm that affects the colon or rectum. "Finally, RPL24, which we found elevated across our analyses, is known to enhance translation and promote tumorigenesis; its functional inactivation through mutation suppressed colorectal cancer by promoting eEF2 phosphorylation via eEF2K." (PMID 37888706, 2023). "Expression of RPL24, EEF2K, and EEF2 is consistent with increased eEF2 activity in colorectal cancer (CRC) tumours." (PMID 34895463, 2021).
hepatocellular carcinoma (2 papers, 2017 to 2023). A malignant tumor that arises from hepatocytes. "RPL24 recombinant protein has a significant tumor-suppressor effect in tumor-bearing mice and the human hepatocellular carcinoma HepG2 cell line." (PMID 37920171, 2023). "In addition, RPL24 overexpression may confer some amycin resistance in the human hepatocellular carcinoma HepG2 cell line, according to the same research findings." (PMID 37920171, 2023). "To date, eL36 (rpL36) plays a role in cisplatin resistance in human carcinoma cells, the radiosensitivity in NSCLC (non-small cell lung cancer) cells is regulated by uS3 (rpS3), and eL24 (rpL24) may have effects on drug resistance mechanisms in hepatocellular carcinoma HepG2 cells." (PMID 28273808, 2017).
thyroid (2 papers, 2020 to 2022). "According to this finding, it is possible that low expression of RPL24 could be correlated with good prognosis of cancers such as thyroid and renal cell cancers (The Human Genome Atlas)." (PMID 32039517, 2020). "No previous association with thyroid disease has been reported for the remaining five proteins: sialic acid acetylesterase (SIAE), hepatocyte growth factor-regulated tyrosine kinase substrate (HGS), Myotrophin (MTPN), 60S ribosomal protein L24 (RPL24), and Coronin-7 (CORO7)." (PMID 36068205, 2022).
viral infection (2 papers, 2021 to 2023). "The association of ribosomal proteins such as RPL6, RPL18 and RPL24 along with other RPs has been reported as an essential step in translational transactivation in plants and animals upon viral infection." (PMID 36616305, 2023). "Different RPs like RPL10, RPL13, RPL18, RPL24, and RPS6 are involved in viral infections of plants." (PMID 33995313, 2021).
bladder cancer (1 paper, 2021). "We conducted a survival study using BBN in the 2 murine cohorts and observed a significant delay in bladder cancer–related deaths in rpL24+/– mice." (PMID 34032633, 2021). "The first WT mouse died from bladder cancer after 69 days of starting BBN, while the first reported death in rpL24+/– mice occurred after 140 days." (PMID 34032633, 2021).
bladder tumor (1 paper, 2021). "In order to determine if robust protein synthesis is necessary for bladder tumor formation, we used a mouse model haploinsufficient for the ribosomal protein L24 (rpL24+/–)." (PMID 34032633, 2021).
colon adenocarcinoma (1 paper, 2021). "Similar results are seen for the protein expression of RPL24, eEF2K, and eEF2 from colon adenocarcinoma samples, and for the three mRNAs in rectal adenocarcinoma." (PMID 34895463, 2021). "(B) RNA expression levels of RPL24, EEF2K, and EEF2 between normal colon and colon adenocarcinoma samples using data extracted from The Cancer Genome Atlas by TNMplot." (PMID 34895463, 2021).
intestinal tumour (1 paper, 2021). "In parallel to analysing the effect of Rpl24 mutation in Apc-deficient Kras-mutant intestinal tumours, we also assessed its role in Apc-deficient models wild-type for Kras." (PMID 34895463, 2021).
liver cancer (1 paper, 2021). An epithelial or non-epithelial malignant neoplasm that arises from the liver. "In addition, the ribosomal protein L24 seems to play a vital role in drug tolerance in human liver cancer HepG2 cell line." (PMID 33500332, 2021).
lymph node metastasis (1 paper, 2024). "Among the aberrantly expressed ribosomal proteins in LSCC tissues with lymph node metastasis, RPS10 and RPL24 are significantly prominent and are considered biomarkers for lymph node metastasis." (PMID 38787142, 2024).
optic nerve hypoplasia (1 paper, 2010). "If translation of the GC-rich Math5 mRNA were hypersensitive to ribosome functional status, this may contribute to the disruption of RGC development in Bst/+ mice, which have a mutation in the Rpl24 riboprotein gene and severe optic nerve hypoplasia." (PMID 20808762, 2010).
ovarian carcinoma (1 paper, 2025). A malignant neoplasm originating from the surface ovarian epithelium. "Moreover, we showed that PARP16, a tail-anchored endoplasmic reticulum-associated protein, is a MART that MARylates RPS6 and RPL24 in ovarian cancer cells to control the loading of mRNAs on ribosomes and their translation." (PMID 39760726, 2025). "In ovarian cancer cells, PARP16 uses NAD+ produced by the cytosolic NAD+ synthase NMNAT-2 to MARylate RPS6 and RPL24." (PMID 39760726, 2025).
prostate carcinoma (1 paper, 2022). A carcinoma that arises from epithelial cells of the prostate gland. "Other ribosomal proteins have been reported in prostate cancer pathogenesis, such as RPL19, RPL21, and RPL24, and have been proposed as good prostate cancer biomarkers." (PMID 36140189, 2022).
urothelial carcinoma (1 paper, 2021). A malignant neoplasm derived from the transitional epithelium of the urinary tract (urinary bladder, ureter, urethra, or renal pelvis). "Using the puromycin incorporation assay to measure de novo protein synthesis in vivo, we observed that rpL24+/– mice display a 60% decrease in protein synthesis within bladder urothelium, the tissue of origin for urothelial carcinoma, compared with WT mice." (PMID 34032633, 2021).
cancer (11 papers, 2014 to 2024). A tumor composed of atypical neoplastic, often pleomorphic cells that invade other tissues. "Partial loss of large ribosomal subunit protein 24 (RPL24) function is known to protect mice against Akt or Myc-driven cancers, in part via translational inhibition of a subset of cap(eIF4E)-dependently translated mRNAs." (PMID 24970821, 2014). "Partial loss of RPL24 function is known to protect mice against Akt or Myc-driven cancers." (PMID 37888706, 2023). "The fact that homozygous loss of RPL24 is embryonic lethal might cause concern about developing a target-specific anti-RPL24 cancer therapeutic." (PMID 24970821, 2014). "Our findings also indicate that the mechanism of action by which RPL24 deficiency reduces expression of these proteins essential for cancer cell viability involves failure of 40S and 60S ribosomal subunit joining into functional 80S ribosomes by retention of eIF6 on 60S subunits." (PMID 24970821, 2014). "The Rpl24Bst mutant mouse reduces the expression of the ribosomal protein RPL24 and has been used to suppress translation and limit tumorigenesis in multiple mouse models of cancer." (PMID 34895463, 2021). "This presents the possibility of directly targeting either RPL24 or eEF2 for anti-cancer benefit." (PMID 34895463, 2021). "Thus, while the role of RPL24 in tumorigenesis has so far been attributed to its involvement in translation, our current findings suggest RPL24 regulation of a specific set of miRs as potentially contributing to various cancers." (PMID 38261097, 2024). "Among nine candidate oncogenes, high expression of four genes including RFTN1, HMGB1, RPL24, and RPL31 were reported to be correlated with a poorer prognosis in cancers (conversely, one may say that low expression of such genes shows good prognosis)." (PMID 32039517, 2020). "We demonstrate that RPL24 depletion decreases the level of proteins synthesized by cap-dependent translation essential for cancer cell growth, survival and genome repair, without altering the synthesis of housekeeping proteins." (PMID 24970821, 2014).
tumor (5 papers, 2014 to 2024). "We showed that RPL24 overexpression can reduce the growth and tumor formation rate of the mice, indicating that the low-RPL24 expression group had a poor prognosis." (PMID 37920171, 2023). "Subsequently a mouse CC model was constructed showing that high RPL24 expression can//’/’ inhibit tumor formation rate in mice, which suggested that RPL24 has a tumor-suppressive effect in CC." (PMID 37920171, 2023). "Simultaneously, a nude mouse xenograft model was used to examine the effect of RPL24 on tumor growth in vivo, which showed that overexpression of RPL24 can suppress tumor growth." (PMID 37920171, 2023). "Suppression of protein synthesis was sufficient to slow tumorigenesis, with some Rpl24Bst/+ mice surviving over three times longer than the median survival of tumour model mice wild-type for Rpl24." (PMID 34895463, 2021). "We provide genetic evidence supported by molecular assays of translation elongation to demonstrate that RPL24 depletion activates eEF2K to elicit tumour suppression in our models." (PMID 34895463, 2021). "Interpreting this molecular analysis in conjunction with the effects on tumorigenesis leads to the conclusion that RPL24 expression maintains translation elongation and protein synthesis rates, which in turn maintain tumour-related proliferation." (PMID 34895463, 2021). "Studies of RPL24 haploinsufficient mice protected from Myc-driven tumorigenesis revealed that dysregulated cap-dependent protein synthesis not only induces tumor formation but also results in cell cycle dysregulation and genomic instability." (PMID 24970821, 2014). "The entire group of tumor samples exhibited a significant 20% mean overall increase in RPL24 expression levels (p = 0.001), indicating that transcriptional upregulation of RPL24 commonly occurs in human breast tumorigenesis." (PMID 24970821, 2014). "Therefore, to evaluate the role of RPL24 in tumorigenesis in vivo, a tumor xenograft nude mice model was constructed." (PMID 37920171, 2023). "To address any potential bias in protein quantification due to variations in tumor purity, we conducted immunohistochemical (IHC) analyses for RPS10 and RPL24, which were consistent with our Western blot results." (PMID 38787142, 2024). "Moreover, HDAC inhibitors used as conventional epigenetic drugs for tumor treatment, such as trichostatin-A (TSA), can inhibit the malignant proliferation of tumors through downregulation of RPL24 expression by inducing acetylation." (PMID 37920171, 2023). "There was no alteration in the number or cumulative size of tumours in the ageing model at endpoint, again identifying tumour cell proliferation, rather than tumour initiation, as the principal factor regulated by RPL24 and eEF2K." (PMID 34895463, 2021).
infection (3 papers, 2017 to 2023). The state of being infected such as from the introduction of a foreign agent such as serum, vaccine, antigenic substance or organism. "We found that two variants were nominally associated with the risk of severe disease among cases (rs11919389 near RPL24, P = 0.029 and rs1886814 near FOXP4, P = 0.018), suggesting that these loci also modulate disease severity after infection with SARS-CoV-2." (PMID 35241825, 2022). "We observed that under all the conditions tested (mock infection, 6 hpi, and 18 hpi), cytoplasmic ribosome proteins from the small (RPS6, RPS14, and RPS3) and large (RPL23a, RPL24, and RPL8) subunits were enriched in the ASFV-DP fraction." (PMID 29021398, 2017).
blood cancer (1 paper, 2021). "We have shown that in mouse models of CRC the molecular mechanism by which normal levels of RPL24 maintain translation is via eEF2K and P-eEF2, therefore implicating this pathway in these previously studied blood cancer models." (PMID 34895463, 2021). "We also speculate as to the role of eEF2K in the previously published blood cancer models where RPL24 depletion was beneficial." (PMID 34895463, 2021).
RPL24 also shares sentences with these, for which no sentence is quoted: cervical tumor (1 paper); lung adenocarcinoma (1); rectal adenocarcinoma (1); renal cell cancers (1); thyroid cancer (1); thyroid nodule (1).